CTHRC1 (collagen triple helix repeat containing 1)
Diseases named in the same sentence as CTHRC1 in open-access papers (continued):
Sharing a sentence is not in itself a finding about the gene and the disease.
tumor (continued). "CTHRC1 may assist tumor cells in evading detection and destruction by the immune system, potentially through mechanisms such as suppressing immune responses, reducing immune cell infiltration into the tumor, or modifying the tumor microenvironment to promote tumor growth." (PMID 40445003, 2025). "Proteins such as periostin (POSTN), versican (VCAN), collagen type XI alpha 1 (COL11A1), and collagen triple helix repeat containing-1 (CTHRC1), through TGF-β signaling, participate in CAF activation and promote tumor progression." (PMID 40136652, 2025). "The results showed that the expression levels of CTHRC1, APOD, and S100A12 in the tumor group were significantly upregulated, whereas the expression levels of ASCL2 in the tumor group were significantly downregulated." (PMID 40898459, 2025). "RT-qPCR and Western blot analyses confirmed that CTHRC1, APOD, and S100A12 expression was significantly upregulated in the tumor group, while ASCL2 expression was significantly downregulated." (PMID 40898459, 2025). "To further investigate the types of cells expressing CTHRC1, CST6, and AKR1B1 in tumor tissues, we utilized the GEO database datasets EMTAB8107 and GSE167297 to conduct a detailed analysis of CTHRC1, CST6, and AKR1B1 expression in STAD." (PMID 40978044, 2025). "Reverse transcription quantitative polymerase chain reaction and Western blot analyses confirmed that CTHRC1, APOD, and S100A12 were significantly upregulated in the tumor group, whereas ASCL2 expression was significantly downregulated." (PMID 40898459, 2025). "Their studies have demonstrated that the upregulation of CTHRC1, VCAN, and POSTN plays a pivotal role in the initiation of angiogenesis, hence facilitating the provision of essential nutrients to tumor cells." (PMID 38420016, 2024). "Research indicates that CTHRC1 is overexpressed in HCC tissues and correlates with poor clinical outcomes, including larger tumor size and increased metastasis." (PMID 39839798, 2024). "Analysis of tumor-infiltrating immune cells was conducted to unveil the relationship between the TME and CTHRC1 expression, aiming to identify a novel gene marker for the early diagnosis and treatment of HNSCC." (PMID 38937712, 2024). "FN1 was also an important gene in CTHRC1+GREM1+ myCAF, which has been shown to promote angiogenesis and metastasis of tumor cells through integrin signaling, leading to the activation of the FAK pathway and also contributing to EMT39." (PMID 39075108, 2024). "The expression of CTHRC1 is influenced by various signaling pathways, including TGF-β and PI3K/AKT, which are known to promote tumor progression and epithelial-mesenchymal transition (EMT)." (PMID 39839798, 2024). "Most genes related to CTHRC1 in HNSCC were enriched in physiological functions of Extracellular matrix(ECM) and tumor." (PMID 38937712, 2024). "Our investigation has revealed that CTHRC1 plays a critical role in promoting the progression of ATC by upregulating the proliferation, migration, and invasion of tumor cells." (PMID 37273536, 2023). "Collagen triple helix repeat containing 1 (CTHRC1), an extracellular matrix protein, is involved in the pathogenesis of vascular remodeling, bone formation, and tumor progression." (PMID 36923925, 2023). "The anti-CTHRC1 antibody was shown to reverse PSC activation and CAF differentiation, and to suppress tumor growth in animal models." (PMID 37444482, 2023). "[CONCLUSION] PSC activation was demonstrated to be the key molecular mechanism responsible for the tumor-promoting effects of CTHRC1, and CTHRC1 has a critical role in CAF subtype differentiation and tumor microenvironment (TME) remodeling." (PMID 37444482, 2023). "CTHRC1 overexpresses in HCC samples, which can promote tumor invasion, proliferation, and motility and predicts poor prognosis." (PMID 35840618, 2022). "Specifically in PCa, miR‐30e exhibited a tumor suppressor role by targeting genes such as CHRM3, CTHRC1 and genes in MAPK signaling pathway." (PMID 35612714, 2022).
tumor (continued). "The infiltration of macrophages, neutrophils, and dendritic cells are positively correlated with these COL8A1, COL10A1, CTHRC1, and FAP, suggesting the need for exploration of their roles in the tumor microenvironment of GC." (PMID 35910202, 2022). "Statistical analysis of this change across tumour grades by ANOVA showed all hub genes and CTHRC1 expression to indeed be tumour stage-dependent." (PMID 36190948, 2022). "Hence, the interaction network between CTHRC1 and Wnt/β-catenin might accelerate tumor progression." (PMID 34702252, 2021). "Six tumor antigens (THBS2, FSTL3, TNNT1, BGN, CTHRC1, and NOX4) were identified as potential therapeutic candidates for the anti-CRC mRNA vaccine that can be processed and presented by APCs to activate a robust immune response." (PMID 35127707, 2021). "The expression of the tumor angiogenesis marker CD31 and stroma-related protein CTHRC1 were analyzed using immunohistochemistry (IHC) assay to evaluate differences between the two groups." (PMID 33718237, 2021). "We also explored few interesting correlations between CTHRC1 expression and promoter methylation, genetic alterations, CNVs, CD8+ T immune cells infiltration, and tumor purity." (PMID 34615943, 2021). "In short, CTHRC1 can affect the expression of HIF-1α, which is not only related to lymphangiogenesis but also closely related to tumor progression and invasion." (PMID 32848510, 2020). "It downregulates the CTHRC1-mediated GSK-3β/β-catenin signal and inhibits tumor cell proliferation, invasion, and migration." (PMID 32848510, 2020). "Further, treatment with MEK1/2 inhibitors can reduce tumor cell invasion, and ERK activation and aggressiveness are reduced by knocking down CTHRC1." (PMID 32848510, 2020). "CTHRC1, a secreted collagen triple helix filament that forms a complex that stabilizes WNT binding to its tumor‐expressed receptor‐FZD, was specifically expressed by CAFs." (PMID 33332768, 2020). "The control tumors showed diffuse CTHRC1 staining in tumor cells and a more prominent staining around tumor blood vessels, while the P4HA1‐KD tumors showed reduced CTHRC1 staining especially around tumor blood vessels." (PMID 32053263, 2020). "Highly expressed CTHRC1 promotes epithelial-mesenchymal transition (EMT) and tumor metastasis through the Smad2/Smad3 activation of TGF-β pathway." (PMID 32848510, 2020). "As we all know, CTHRC1 is a secreted ECM protein, which can inhibit collagen deposition and participate in tumor invasion and metastasis." (PMID 32848510, 2020). "However, the relationship between CTHRC1 expression and tumor angiogenesis in LUAD remains unclear." (PMID 31798347, 2019). "The correlation between CTHRC1 and MMP7 and MMP9 expression was further confirmed by IHC results obtained from 230 clinical NSCLC tumour samples." (PMID 29631554, 2018). "Consistent with the ELISA data, CTHRC1 expression was significantly correlated with MMP7 and MMP9 expression in primary tumour tissues." (PMID 29631554, 2018). "As a candidate tumour marker in this study, CTHRC1 was identified in NSCLC samples by performing quantitative assessments involving 2D-PAGE gels and mass spectrometry in comparison with adjacent non-tumour tissues." (PMID 29631554, 2018). "As shown in the present study, significantly higher expression of CTHRC1, MMP-7 and MMP-9 was observed in a cohort of NSCLC sera and surgically resected tumour tissues." (PMID 29631554, 2018). "These accumulating data indicated that CTHRC1 was a key regulator of HCC invasion and metastasis through EMT change and modulation of MMP expression in the tumor microenvironment." (PMID 29285247, 2017). "Also, the inhibition of FAK could suppress the effect of CTHRC1 on i.p tumor seeding in vivo." (PMID 29021002, 2017). "However, the angiogenetic function of CTHRC1 in the tumor microenvironment remains unclear." (PMID 27686285, 2016).
tumor (continued). "The gene list they identified shares similarities to gene expressed in our whole tumour sample (ANTXR1, COL12A1, COL5A2, CTHRC1, POSTN)." (PMID 19401702, 2009). "To validate our computational findings, we performed experimental validation using qRT-PCR, confirming significant overexpression of CTHRC1, CST6, and AKR1B1 in GC tissues compared to adjacent normal tissues (p < 0.05), with HPA data further confirming elevated protein levels in tumor tissues." (PMID 40978044, 2025). "Moreover, our data suggest a potential crucial role for CTHRC1, CST6, and AKR1B1 in the mitochondria process of tumor cells." (PMID 40978044, 2025). "In contrast, C1 CTHRC1+ fibroblasts and C7 PCLAF+ fibroblasts predominantly originated from tumor tissues (C and LN), suggesting that they may be malignant fibroblasts." (PMID 41035818, 2025). "In particular, CTHRC1+GREM1+ myCAF expressed high levels of collagens, including type-1 (COL1A1, COL1A6), type-3 (COL3A1), type-5 (COL5A2), and type-6 (COL6A1), which contribute to tumor cell migration and proliferation through collagen/integrin interactions." (PMID 39075108, 2024). "We verified this by plotting the CTHRC1+GREM1+ myCAF, SPP1+APOE+ TAM, and EMT signatures from previous parts of our study, which showed clear overlays, supporting the co-localization of fibroblasts and macrophages while promoting the pro-tumor TME." (PMID 39075108, 2024). "We also observed increased expression of proteoglycans such as CTHRC1 and THBS2 that were unique to myCAF, which have both been determined to contribute to EMT through the Wnt/b-catenin and NF-kB pathways, leading to tumor invasiveness and poor survival." (PMID 39075108, 2024). "To address this hypothesis, we first conducted expression plots of CTHRC1, GREM1, SPP1, and APOE in the TCGA cohort, which were all significantly enriched in tumor samples versus control." (PMID 39075108, 2024). "Survival analysis of CTHRC1 and SPP1 gene expression in PAAD demonstrated that patients with high expression of these genes led to worse survival, demonstrating the pro-tumor functions of these genes in the clinical context." (PMID 39075108, 2024). "Similarly, CTHRC1+GREM1+ myCAF communicated with SPP1+ macrophages and tumor cells through integrin signaling, where collagen/integrin pairs and FN1/integrin pairs were prevalent." (PMID 39075108, 2024). "Further analysis revealed that EMT was an extremely significant mechanism regulated by CTHRC1+GREM1+ myCAF, indicating these fibroblasts support cancerous cell differentiation and proliferation leading to rapid tumor growth and potential metastasis." (PMID 39075108, 2024). "The tumor gene expression analyses showed that anti-CTHRC1 suppressed myCAF markers in tumor tissues; however, no suppression reached statistical significance." (PMID 37444482, 2023). "These include CTHRC1, INHBA, BGN, and PDPN, all of which are known to promote tumor progression." (PMID 38036590, 2023). "This suggests that the tumor-promoting effects of CTHRC1 is largely dependent on its stimulation of PSCs rather than on its autocrine effects." (PMID 37444482, 2023). "CTHRC1 with POSTN and MMP13 could potentially affect ECM remodelling which in turn could aid in tumor cell migration and invasion." (PMID 36190948, 2022). "Therefore, the expression of CTHRC1 in COAD at the mRNA and protein levels was investigated using various tumour databases." (PMID 35300110, 2022). "It has been reported that high expression of CTHRC1 was meaningfully correlated with metastasis in patients with NSCLC and that over-expression of CTHRC1 might be involved in tumor poor prognosis and angiogenesis in LUAD." (PMID 35246517, 2022). "In conclusion, through comprehensive bioinformatics analysis, we successfully identified three hub genes (CTHRC1, FNDC1, and INHBA) that are differentially expressed between tumor and normal tissues in both TCGA-STAD and GSE66229 datasets and highly correlated with GC." (PMID 34968391, 2021).
tumor (continued). "We first performed an analysis of the pattern of CTHRC1 expression in various normal tissues and tumor/nontumor cells." (PMID 34702252, 2021). "Furthermore, we utilized the TIMER database to find the Spearman correlation between CTHRC1 expression and CD8+ T cells infiltration and tumor purity." (PMID 34615943, 2021). "A recent study demonstrated that CTHRC1 could promote ERK and JNK phosphorylation by activating PCP signaling pathways in human umbilical vein endothelial cells (HUVECs) and promote tumor angiogenesis." (PMID 32848510, 2020). "Current reports indicate that CTHRC1 is mainly involved in tumor progression through the canonical Wnt/β-catenin and noncanonical Wnt/PCP pathways." (PMID 32848510, 2020). "In addition, hypoxia-inducible factor 1α (HIF-1α) and vascular endothelial growth factor (VEGF) are activated by CTHRC1 through activating the PI3K/AKT/mammalian target of rapamycin (mTOR) signaling pathway, which promotes tumor angiogenesis." (PMID 32848510, 2020). "Thus, we concluded that miR-155-5p negatively mediated tumor growth and metastasis of HCC in vitro by CTHRC1 modulation." (PMID 29234238, 2017). "IHC findings were observed according to tumor differentiation in tissue microarrays (TMA) from an independent cohort of patients; CTHRC1 expression was barely detected in normal tissue, but moderate and strong expression was seen in HCC with poor differentiation." (PMID 29285247, 2017). "A pyrosequencing assay revealed a CpG site (cg07757887, -1220 bp in the CTHRC1 genomic region) hypomethylated in ESCC tumour tissues, which has not been previously reported as being related to cancer." (PMID 28645305, 2017). "CTHRC1 was also detectable in the serum of HCC patients, compared with non-tumor controls." (PMID 29285247, 2017). "Compared to matched non-tumor tissues, 94% (158/169) of tumour tissues exhibited stronger staining of CTHRC1." (PMID 28645305, 2017). "Secreted CTHRC1 overproduced in cancer cells may act on the surrounding microenvironment, such as stromal cells and ECM, to promote tumor invasion and metastasis." (PMID 29285247, 2017). "Since the interactions of tumor cells with the extracellular matrix (ECM) are a crucial step in invasion and metastasis, we further examined whether CTHRC1 expression could influence the adhesion capability of EOC cells." (PMID 29021002, 2017). "Promoter hypomethylation at cg07757887 may contribute to increased CTHRC1 expression in ESCC cells and tumours." (PMID 28645305, 2017). "IHC showed slight cytoplasmic staining of CTHRC1 protein in normal oesophageal epithelial cells, whereas moderate to strong staining in the cytoplasm and extracellular space was observed in most ESCC tumour tissues." (PMID 28645305, 2017). "Immunostaining of the DNA synthesis marker, minichromosome maintenance complex component 7 (MCM7), appeared to show increased intensity in the CTHRC1-knockdown tumors as compared to the control tumors, regardless of the tumor size." (PMID 26918341, 2016). "Using rigorously validated monoclonal Cthrc1 antibodies we demonstrate that in all of our cases Cthrc1 expression in human cancers originates from activated stromal cells, not the tumor cells themselves." (PMID 24945147, 2014). "Several previous studies have suggested that CTHRC1 is related to the motility and invasion of both non-tumor and tumor cells." (PMID 24841500, 2014). "In none of the specimens examined did we ever find Cthrc1 in the parenchymal cells or the tumor cells themselves." (PMID 24945147, 2014). "When injected into NOD/SCID mice, HA22T cells with or without CTHRC1 knockdown cannot form tumor up to 8 weeks after injection (data not shown)." (PMID 23922981, 2013).
tumor (continued). "Thus, we have established the monumental impact of these macrophages in the immuno-suppresive, pro-fibrotic niche, which we hypothesize may help support the role of CTHRC1+GREM1+ myCAF and tumor cells further through EMT and other pro-tumor mechanisms." (PMID 39075108, 2024). "In addition, CTHRC1 and ADAM12, which were highly expressed in C02_POSTN and C07_MKI67 could promote tumour progression, and affect the infiltration of immune cells and polarization of M2 macrophages." (PMID 38115703, 2023). "Therefore, we investigated whether the expression of THBS2, FSTL3, TNNT1, BGN, CTHRC1, and NOX4 was correlated with immune cell infiltration levels in CRC via the Tumor Immune Estimation Resource (TIMER) database." (PMID 35127707, 2021). "Interestingly, we revealed that there is a close correlation between CTHRC1 expression and CD8+ T immune infiltration, which may contribute to the development of HNSC, KIRC, LIHC, LUAD, STAD, and UCEC by affecting the tumor microenvironment." (PMID 34615943, 2021). "Interestingly, of the few genes that, via sPLS-DA, were predicted to contribute to tumor regression at certain stage-to-stage interfaces—including DAPK2, PLAC9, ABCB9, MELTF, CTHRC1, and OCIAD2, testing for LUAD patient survivability via AK4 combination resulted in a negative prognosis." (PMID 34940617, 2021). "More accurately, tumor stroma might play an important role in negative immunoregulation since the hub genes (i.e., CTHRC1, COL1A1, LOXL2, P4HA3, and FKBP10) related to immunosuppressive GO terms usually participate in collagen formation." (PMID 33791227, 2021). "Furthermore, our study provides a new mechanism that CTHRC1 may affect the prognosis of KIRP and KIRC through tumor immune infiltration." (PMID 33628726, 2020). "Therefore, another mechanism by which CTHRC1 promotes tumor invasion may be related to its role in reducing the cleavage of collagen by ECM-digesting components, thus making it easier for tumor cells to migrate into the adjacent tissues." (PMID 24504172, 2014). "Overexpression of CTHRC1 in Huh7 cells did not enhance tumor growth in NOD/SCID mice." (PMID 23922981, 2013). "Additionally, ECM‐bound molecules like collagen triple helix repeat containing 1 (CTHRC1) and transforming growth factor‐beta‐induced protein (TGFBI), secreted by fibroblasts, can modulate macrophage activity and cytokine production, which in turn affects tumor immune responses." (PMID 40686923, 2025). "Furthermore, CTHRC1 has been shown to enhance GC metastasis via the HIF-1α/CXCR4 signaling pathway; it upregulates CXCR4 expression through HIF-1α and facilitates the migration and invasion of cancer cells, promoting tumor spread to distant organs, thus playing a crucial role in metastasis." (PMID 40978044, 2025). "Thus, it is possible that the secreted form of CTHRC1 overproduced through ALV-J-infection may act on the surrounding microenvironment, including the stromal cells and extracellular matrix (ECM), which elevates tumor invasion and migration." (PMID 33102569, 2020). "However, we observed that optiCA1 overexpressing tumor cells, when compared with the controls, had not statistically changed expression profile of mRNAs (COL1A1, COL4A4, LAMC2, CTHRC1, and WNT7B)." (PMID 31963697, 2020).